WT1 (WT1 transcription factor)
Diseases named in the same sentence as WT1 in open-access papers (continued):
Sharing a sentence is not in itself a finding about the gene and the disease.
dermatofibrosarcoma protuberans (1 paper, 2021). Dermatofibrosarcoma protuberans (DFSP) is a rare infiltrating soft tissue sarcoma, generally of low grade malignancy, arising from the dermis of the skin and characteristically associated with a specific chromosomal translocation t(17;22). "Interestingly, the neoplastic cells of both the fibrosarcomatous and giant cell fibroblastoma components, found in two and three cases, respectively, were strongly and diffusely stained with WT1." (PMID 33445443, 2021).
desmoid tumor (1 paper, 2019). A desmoid tumor (DT) is a benign, locally invasive soft tissue tumor associated with a high recurrence rate but with no metastatic potential. "In addition, the abnormal expression of WT1 by tissues that don’t usually express it results in highly proliferative neoplasms, such as the desmoid tumors, i.e. WT1 is considered an oncogene when it’s expressed abnormally." (PMID 31760217, 2019).
diffuse astrocytoma (1 paper, 2020). A low-grade (WHO grade II) astrocytic neoplasm. "About 81.8% of grade II diffuse astrocytomas expressed WT1 with a highly significant difference (p<0.001) and diagnostic accuracy of 93.5% when compared to reactive astrogliosis." (PMID 32856872, 2020). "Low WT1 scores in grade II and III diffuse astrocytomas were linked to the high frequency of IDH1 positivity, and were associated with low Bcl2 and Ki67 labelling indices." (PMID 32856872, 2020). "Likewise, WT1 differentiated grade II diffuse astrocytoma from astrogliosis with an accuracy of 93.5% and a 100% PPV." (PMID 32856872, 2020).
diffuse large B-cell lymphoma (1 paper, 2014). "In diffuse large B-cell lymphoma the most common type of NHL, WT1 protein was detected in only 33% of the cases examined." (PMID 24589652, 2014).
duodenal cancer (1 paper, 2024). "We report a case in which the combination of a WT1/MUC1-DC vaccine and CAT was highly efficacious in the treatment of unresectable duodenal cancer with peritoneal dissemination and malignant ascites that had proven refractory to chemotherapy." (PMID 39737308, 2024). "This case suggests a possible beneficial effect of adoptive cell therapy with WT1/MUC1-DC and CAT for peritoneal dissemination and malignant ascites in duodenal cancer." (PMID 39737308, 2024). "Therefore, the combination of WT1/MUC1-DC and CAT may enhance the antitumor immune response to duodenal cancer." (PMID 39737308, 2024).
Dysmenorrhea (1 paper, 2023). Pain during menstruation that interferes with daily activities. "Finally, the WT1 gene encodes a zinc-finger-containing transcription factor that regulates female fertility and has recently been linked with EM-associated dysmenorrhea." (PMID 37626618, 2023).
endometrial adenocarcinomas (1 paper, 2020). "In fact, a significant proportion of endometrial adenocarcinomas can also show WT1 immunoreactivity." (PMID 32859123, 2020).
endothelial dysfunction (1 paper, 2024). In vascular diseases, endothelial dysfunction is a systemic pathological state of the endothelium (the inner lining of blood vessels) and can be broadly defined as an imbalance between vasodilating and vasoconstricting substances produced by (or acting on) the endothelium. "We hypothesize that our patient's WT1 mutations resulted in a podocytopathy that led to endothelial dysfunction, which, combined in one patient with CFHR1,4, culminated in the development of aHUS." (PMID 39445256, 2024).
epidermoid cysts (1 paper, 2018). "Mesothelial cysts are lined by cells that stain positive for markers such as calretinin or WT-1 and negative for endothelial markers, whereas epidermoid cysts are lined by epithelial cells positive for cytokeratins." (PMID 29656712, 2018).
extraskeletal myxoid chondrosarcoma (1 paper, 2010). A rare malignant soft tissue neoplasm of uncertain differentiation, characterized by the presence of chondroblast-like cells in a myxoid stroma and a multinodular growth pattern. "Additional FISH assays for WT1, CHN and DDIT3 (3' partners of EWSR1 in desmoplastic round cell tumor, extraskeletal myxoid chondrosarcoma and round cell liposarcoma, respectively) were negative." (PMID 20598147, 2010).
fibroids (1 paper, 2025). "WT1 has been previously associated with fibroids but not in this population." (PMID 40050615, 2025).
gastric adenocarcinoma (1 paper, 2023). "Our findings indicate that both intestinal and diffuse-subtype gastric adenocarcinomas are susceptible to RV Wt1-5 infections and that RV efficiently infects these tumors." (PMID 37186587, 2023). "In this study, we investigated the interaction of RV Wt1-5 with the tumor microenvironment using an ex vivo human gastric adenocarcinoma explant model for the first time." (PMID 37186587, 2023). "This study aimed to examine the oncolytic potential of tumor cell-adapted rotavirus Wt1-5 in gastric adenocarcinoma samples." (PMID 37186587, 2023). "This study demonstrates that after 12 hours, RV Wt1-5 had spread throughout the depth of intestinal and diffuse-subtype gastric adenocarcinomas, including structures such as nerve tissue and blood vessels, and that the tumor cells were significantly more infected than the adjacent non-tumor cells." (PMID 37186587, 2023).
gastrointestinal stromal tumor (1 paper, 2025). "Immunohistochemical analysis showed that the tumors were positive for vimentin, WT1, progesterone receptor (PR), and variably for estrogen receptor (ER), CD56, inhibin, and calretinin, while being negative for markers of epithelial, melanocytic, and gastrointestinal stromal tumors." (PMID 40828576, 2025).
HCMV infection (1 paper, 2023). "HCMV infection mediates the upregulation of Wilms’ tumor 1 (WT1) protein, a transcription factor associated with the negative regulation of EGFR." (PMID 38136637, 2023). "The binding of WT1 to the EGFR promoter also increases during HCMV infection, while depletion of WT1 suppresses HCMV-induced negative regulation of EGFR." (PMID 38136637, 2023).
head and neck carcinoma (1 paper, 2023). A carcinoma that arises from the head and neck region. "Among these interacted genes, the expression of WT1 had a statistical relationship with the overall survival of patients with head and neck carcinoma in the TCGA database (p = 0.019)." (PMID 36983712, 2023). "By reviewing the literature, WT1 drew our attention, and based on the TCGA database, WT1 is the only one among the interacted genes that had a statistical relationship with the survival of patients with head and neck carcinoma." (PMID 36983712, 2023).
Hepatitis C (1 paper, 2025). "In previous studies, it has been reported that such polyvalent candidates showed substantial activity against Wilms tumor-1 (WT1) and human papillomavirus (HPV) cancer against Hepatitis C." (PMID 39752339, 2025).
hereditary cancer (1 paper, 2025). Malignant neoplasms occurring in families at a rate greater than that expected by chance and caused by germline mutations in a specific gene. "LP/P findings in pleiotropic genes linked to human development and hereditary cancer (TSC1, PHOX2B, WT1, SPRED1, NF1, LZTR1, HOXB13) were identified in several patients with syndromic phenotypes." (PMID 40060932, 2025).
hydronephrosis (1 paper, 2013). Collection of urine in the renal pelvis that results in dilatation of the renal pelvis and calyces. "Invariably, the Wt1-Igf2 mice developed hydronephrosis due to tumor-induced obstruction of urine outflow from the renal pelvis or ureters." (PMID 22875335, 2013).
hyperandrogenism (1 paper, 2023). Excessive secretion of androgens from the adrenal glands or gonads. "Hyperandrogenism could affect the window of implantation by decreasing the expression levels of HOXA10 and WT1 genes and influencing endometrial decidualization." (PMID 38033994, 2023).
idiopathic myelofibrosis (1 paper, 2020). "As an example, in idiopathic myelofibrosis (IM), and in PMF it emerged from the analyses that the WT1 gene is highly modulated." (PMID 32331228, 2020).
influenza infection (1 paper, 2023). "Since WT1 (Wilms Tumor Suppressor) is a transcription factor that is downregulated during SARS-CoV-2 infection but not during influenza infection, we focused on the transcriptional effects of its downregulation." (PMID 37561814, 2023). "Importantly, our investigation demonstrated significant downregulation of WT1 during SARS-CoV-2 infection, and that this is not part of the general response observed in respiratory infections as it does not occur in influenza infections." (PMID 37561814, 2023).
invasive carcinoma (1 paper, 2025). A carcinoma that is not confined to the epithelium, and has spread to the surrounding stroma. "Some markers of tubal differentiation present in the endosalpingiosis such as tubulin and OVGP1 are diminished in the invasive carcinoma, which retains expression of WT1, PAX8." (PMID 40940856, 2025).
ischemia reperfusion injury (1 paper, 2023). Adverse functional, metabolic, or structural changes in ischemic tissues resulting from the restoration of blood flow to the tissue (reperfusion), including swelling; hemorrhage; necrosis; and damage from free radicals. "However, in a bilateral renal ischemia-reperfusion injury (IRI) induced AKI mice model, 30.07 ± 1.87% WT1+ cells were localized outside of the glomeruli and co-stained with Lotus tetragonolobus lectin (LTL) after severe AKI." (PMID 36923529, 2023).
Kallman syndrome (1 paper, 2022). "Two nodes representing associated genes were connected to more than one node representing syndromes: the CHD7 gene, associated with both CHARGE and Kallman syndrome, and the WT1 gene, associated with Denys–Drash and Frasier syndrome." (PMID 35218153, 2022).
Kaposi's sarcoma (1 paper, 2024). A malignant neoplasm characterized by a vascular proliferation which usually contains blunt endothelial cells. "Taking our findings together, we propose a model of WT1 mediated tumorigenesis in Kaposi sarcoma in which following KSHV infection, latent viral genes are expressed, including vFLIP, which activate NFκB, leading to upregulation of oncogenic WT1 isoforms." (PMID 38190392, 2024). "This study highlights the overexpression of WT1 in advanced KS cases and a mechanism of KSHV vFLIP- mediated WT1 upregulation and underscores the potential for immunotherapy directed against WT1 as a novel strategy to treat Kaposi sarcoma." (PMID 38190392, 2024). "This study shows that WT1 is overexpressed in the vast majority of Kaposi sarcoma lesions and is largely absent in adjacent normal tissue." (PMID 38190392, 2024).
lupus nephritis (1 paper, 2022). Glomerulonephritis in the context of systemic lupus erythematosus. "Urinary podocyte-specific mRNA markers such as podocalyxin, synaptopodin, podocin, nephrin, as well as WT-1 levels, are significantly elevated in patients with active lupus nephritis compared to those without systemic lupus or active lupus nephritis." (PMID 35886957, 2022).
metabolic syndrome (1 paper, 2021). A cluster of metabolic risk factors for CARDIOVASCULAR DISEASES and TYPE 2 DIABETES MELLITUS. "Furthermore, positive metabolic syndrome criteria were demonstrated in 60% of participants affected by CKD without WT history, suggesting the combination of WT1 abnormalities and metabolic issues are likely the main contributing factors to the CKD development in these patients." (PMID 34970513, 2021).
metastatic prostate carcinoma (1 paper, 2012). A carcinoma that arises from the prostate gland and has spread to other anatomic sites. "Interestingly, another group of targets is associated with germ cells, including Asap1 (Ddef1), which encodes an ADP-ribosylation factor GTPase-activating protein implicated in metastatic prostate cancer, and also the Wilms' tumour gene WT1." (PMID 22479388, 2012).
multiple sclerosis (1 paper, 2021). A progressive autoimmune disorder affecting the central nervous system resulting in demyelination. "PAWR (pro-apoptotic WT1 regulator) is a pro-apoptotic gene that was among the top differentially expressed genes in peripheral blood mononuclear cells (PBMCs) from multiple sclerosis (MS) patients and might be involved in the regulation of MS." (PMID 34349791, 2021).
myasthenia gravis (1 paper, 2023). Myasthenia gravis (MG) is a rare, clinically heterogeneous, autoimmune disorder of the neuromuscular junction characterized by fatigable weakness of voluntary muscles. "Although myasthenia gravis is a well-known complication of TC as a paraneoplastic syndrome, activation of the general immune system by the WT1 Trio may enhance autoimmune responses in the patient." (PMID 36672344, 2023). "The WT1 Trio safety was confirmed without severe treatment-related adverse events, except grade 3 myasthenia gravis-like symptoms observed in a patient with thymic cancer." (PMID 36672344, 2023). "In addition, the safety of WT1 Trio was confirmed without severe treatment-related adverse events, except grade 3 myasthenia gravis-like symptoms observed in a patient with thymic cancer (TC)." (PMID 36672344, 2023).
myelofibrosis (1 paper, 2016). A partial or complete replacement of the bone marrow stroma by fibrous tissue. "In this study we demonstrated that in patients affected by myelofibrosis WT1 correlates with the International Prognostic Scoring System (IPSS) score at diagnosis." (PMID 27167495, 2016). "This study demonstrated that WT1 is a good marker for monitoring the response to therapy in patients affected by myelofibrosis." (PMID 27167495, 2016).
myxoma (1 paper, 2024). A benign soft tissue neoplasm characterized by the presence of spindle and stellate cells, lobulated growth pattern, and myxoid stroma formation. "Myxoma immunohistochemistry demonstrates positivity for S100, CD34 and CD31, while it is negative for markers such as WT1, D2-40 and CK5/6." (PMID 38938650, 2024).
neuroendocrine carcinoma (1 paper, 2024). A malignant neuroendocrine neoplasm composed of cells containing secretory granules that stain positive for NSE and chromogranin. "In addition, the expression of PAX8 (clone SP348), WT1, Napsin A, or TTF1 (clone 8G7G3/1) is never or almost never present in TNBC (the latter outside of the context of neuroendocrine carcinoma)." (PMID 37306115, 2024).
neurofibroma (1 paper, 2021). An intraneural or extraneural neoplasm arising from nerve tissues and neural sheaths. "The results obtained are particularly interesting as only two tumor entities, namely DFSP and neurofibroma, resulted to be positive for WT1, with an expression restricted to the cytoplasm of the neoplastic cells." (PMID 33445443, 2021). "Although differential diagnostic problems do exist between a diffuse neurofibroma infiltrating the dermis and DFSP, the co–expression of both CD34 and WT1 certainly does not help in their distinction." (PMID 33445443, 2021).
oral squamous cell carcinoma (1 paper, 2015). "Immunohistochemical analysis of tissue sections showed overexpression of WT1 protein in two of 29 patients with oral squamous cell carcinoma, suggesting that WT1 plays an important role in the pathogenesis of some types of oral squamous cell carcinoma." (PMID 25929687, 2015).
ovarian adenocarcinoma (1 paper, 2013). An adenocarcinoma that arises from the ovary. "The main positive markers for ovarian adenocarcinomas are ER, PR, CA-125 and Wilm’s tumor 1 (WT1)." (PMID 24137345, 2013).
ovarian diseases (1 paper, 2023). "Some DEGs in F1 ovaries are related to reproductive/ovarian diseases, particularly POI (as Wt1, Bmpr2, Zp1, Zp2) and PCOS (as Tcf21, Fst, Bmpr2)." (PMID 36982971, 2023).
Pancytopenia (1 paper, 2007). An abnormal reduction in numbers of all blood cell types (red blood cells, white blood cells, and platelets). "In contrast, reduction of WT1 peptide dose may be needed for the treatment of patients with hematological stem cell diseases, because rapid and strong destruction of malignant cell-sustained hematopoiesis before recovery of normal hematopoiesis may lead to pancytopenia in these patients." (PMID 17619750, 2007).
pericardial effusion (1 paper, 2015). Fluid collection within the pericardial sac, usually due to inflammation. "The cell-block specimen obtained from his pericardial effusion was positively stained for calretinin, D2-40, and WT1 and negatively stained for CEA." (PMID 26376726, 2015). "Pathological examination of the cell-block specimen obtained from the pericardial effusion revealed malignant mesothelial cells, which were positively stained with calretinin, D2-40, and Wilms’ tumor 1 (WT1) (respectively)." (PMID 26376726, 2015).
pericardial mesothelioma (1 paper, 2023). "In this study, the same clone (6F-H2) of the WT1 antibody was used, which showed positive reactivity against primary cultured cells of canine pericardial mesothelioma." (PMID 38026668, 2023).
plasmacytoma (1 paper, 2023). Plasmacytoma is a localized mass of neoplastic monoclonal plasma cells that represents approximately 5% of all plasma cell neoplasms. "This study confirms the high prevalence of WT1 expression in an Asian cohort of MM, encouraging the development of immunotherapy targeting WT1 in MM patients, particularly in those with extramedullary plasmacytoma or relapsed disease." (PMID 36760714, 2023). "We, therefore, investigated WT1 expression in 142 bone marrow and plasmacytoma samples of MM patients at different stages of the disease by immunohistochemistry." (PMID 36760714, 2023). "In our study, extramedullary tissue expressed higher cytoplasmic WT1, especially at relapse in hematogenous plasmacytoma and plasmacytoma." (PMID 36760714, 2023). "There was an exceptionally high rate of WT1 expression in the cases with hematogenous plasmacytoma and plasmacytoma at the relapse stage, which were difficult to treat." (PMID 36760714, 2023). "The rates of WT1 expressions were 91.3%, 92.0%, 92.1%, and 89.3% in samples at the diagnosis, at relapse, bone marrow, and plasmacytoma, respectively." (PMID 36760714, 2023). "In the plasmacytoma samples (n = 28), soft-tissue plasmacytoma (n = 14) and relapsed plasmacytoma (n = 9) had an exceptional high rate of WT1 protein expression (100%) as compared to bone plasmacytoma (78.6%, n = 11/14) (p = 0.067)." (PMID 36760714, 2023). "In this study, the WT1 expression was investigated by IHC in 142 bone marrow and plasmacytoma samples from a cohort of 95 Thai patients, which is the largest cohort to date." (PMID 36760714, 2023). "However, in a subgroup analysis, the highest cytoplasmic WT1 expression was found in relapsed plasmacytoma samples." (PMID 36760714, 2023). "Moreover, a high rate of WT1 expression was still consistent in the samples at the relapse stage (92%; overall relapsed samples, 100%; relapsed plasmacytoma vs. 91.3% in samples at diagnosis)." (PMID 36760714, 2023). "A further study to clarify whether cytoplasmic retention of WT1 could lead to a decrease in adhesion molecule on MM cells and promote plasmacytoma growth would be of interest." (PMID 36760714, 2023). "The overall positive rate of WT1 expression was 91.5%; this high prevalence was found in both bone marrow and plasmacytoma samples, regardless of the disease status." (PMID 36760714, 2023). "We have shown for the first time that WT1 has high expression rates in both medullary myeloma and plasmacytoma regardless of disease status." (PMID 36760714, 2023). "Our findings support the use of WT1 as a target antigen for immunotherapy in MM and plasmacytoma irrespective of disease status." (PMID 36760714, 2023).
Premature ovarian insufficiency (1 paper, 2023). Amenorrhea due to loss of ovarian function before the age of 40. "Among these genes, ZP1, WT1, and BMPR2 are premature ovarian insufficiency (POI) genes in humans." (PMID 36982971, 2023).